MYB (MYB proto-oncogene, transcription factor)
Diseases named in the same sentence as MYB in open-access papers (continued):
Sharing a sentence is not in itself a finding about the gene and the disease.
Burkitt lymphoma (14 papers, 2017 to 2025). A rare form of malignant mature B-cell non-Hodgkin lymphoma. "The quinoline-based forkhead box protein O1 (FOXO1) inhibitor AS1842856 blocked cell growth, induced apoptosis, and suppressed MYB by upregulation of the tumor suppressor miR-150 in BL-41 and Namalwa Burkitt lymphoma cells." (PMID 38835346, 2024). "The selective JAK2 inhibitor TG101209 induced cell differentiation, apoptosis, and G2/M cell cycle arrest in Raji and Ramos Burkitt lymphoma cells by downregulation of MYB upon inhibition of JAK2/STAT3 signaling." (PMID 38835346, 2024). "We previously showed that MYC promoted Burkitt lymphoma (BL) growth by inhibiting the tumor suppressor miR-150, resulting in release of miR-150 targets MYB and ZDHHC11." (PMID 38627588, 2024). "When a panel of BLBCL, Hodgkin and Burkitt lymphoma cell lines were compared to GCB cells it was revealed that MYC, ZDHHC11/B and MYB were upregulated and miR-150 was downregulated in all lymphoma types as compared to GCB." (PMID 34502399, 2021). "Research in Burkitt lymphoma demonstrated a MYC-miR-150-ZDHHC11/B-MYB network, in which high levels of MYC repress miR-150, which leads to derepression of MYB, ZDHHC11 and ZDHHC11B, and promotes proliferation." (PMID 33593440, 2021). "In Burkitt lymphoma, which is characterized by high MYC expression, two circRNAs, ZDHHC11 and ZDNN11B, containing multiple binding sites for miR-150 were upregulated following upregulation of the MYC that targets MYB." (PMID 34502399, 2021). "In brief, we showed for the first time that TG101209, a specific JAK2 inhibitor, could inhibit Burkitt lymphoma growth, induce cycle arrest, differentiation and apoptosis of BL cells, and prolong the survival of Ramos cell-bearing mice by inhibiting the JAK2/STAT3/c-MYB signaling axis." (PMID 34588425, 2021).
glioblastoma (14 papers, 2013 to 2024). The most malignant astrocytic tumor (WHO grade IV). "In glioblastoma, MYB is an effector of the ZEB-1 pathway, which is implicated in epithelial–mesenchymal transition and key features of cancer stem cells." (PMID 33466745, 2021). "The alkaloid brucine also binds to G-quadruplex sequences of the MYB promoter, leading to MYB suppression, U87 glioblastoma growth inhibition, and cell cycle arrest." (PMID 38835346, 2024). "High levels of ZEB1 downregulated tumor suppressor miR-200c, and low miR-200c induced MYB expression in primary glioblastoma cells, followed by increased O-6-methylguanine DNA methyltransferase (MGMT) expression and DNA repair." (PMID 38835346, 2024). "Using chromatin immunoprecipitation, we confirmed that c-MYB binds to the MGMT promoter in glioblastoma cells." (PMID 23818228, 2013). "Finally, the TCGA dataset supports the prognostic value of the ZEB1/miR-200/c-MYB pathway for glioblastoma, as well as significant co-occurrence of ZEB1, MGMT and ROBO1 in these tumours, and decreased levels of EGFR phosphorylation with reduced ZEB1 expression." (PMID 23818228, 2013). "Two tumors each (3.8%) belonged to the diffuse midline glioma, H3 K27-altered, the diffuse LGG, MYB/MYBL1-altered, and the adult-type glioblastoma, IDH-wt, tumor (sub-)types, respectively." (PMID 38717379, 2024). "Some studies have proved that isomorphic diffuse gliomas have MYB/MYBL1 changes, thus MYB plays an important role in the development of glioblastoma." (PMID 34876130, 2021). "ZEB1 is preferentially expressed in invasive glioblastoma cells, where the ZEB1-miR-200 feedback loop interconnects these processes through the downstream effectors ROBO1, c-MYB and MGMT." (PMID 23818228, 2013).
hepatocellular carcinoma (14 papers, 2010 to 2024). A malignant tumor that arises from hepatocytes. "Consistently, it has been reported that miR-424 targeted c-MYB, and consequently, repressed the invasion and migration of hepatocellular carcinoma cells via c-MYB." (PMID 33407591, 2021). "Previously, MYB was reported as a direct target of miR-150-5p in hepatocellular carcinoma." (PMID 35136029, 2022). "Moreover, up-regulated LINC01287 contributes to growth and invasion of hepatocellular carcinoma cells through miR-298/MYB signaling." (PMID 34229645, 2021). "The ‘-231 ~ -222’ bp region in the promoter of UCA1 is the main binding site of MYB transcription factor in hepatocellular carcinoma cells (HCC)." (PMID 34876130, 2021).
lymphoma (14 papers, 2015 to 2025). A malignant (clonal) proliferation of B- lymphocytes or T- lymphocytes which involves the lymph nodes, bone marrow and/or extranodal sites. "Consistent with this, partial loss of MYB leads to a dramatic loss of B cells, but uncontrolled expression of MYB leads to the development of lymphoid cancers." (PMID 34502399, 2021). "The DAR was 87.5% and MYB was predicted to be associated with lymphoma." (PMID 25932650, 2015). "In this complex pathway, high MYC level downregulates mir-150 expression to protect the oncogenic and lymphoma related MYB from mir-150-mediated repression." (PMID 33544339, 2021). "This together suggests an important role of mir-150 in controlling the oncogenic MYB, a function impaired in cHL and other lymphomas." (PMID 33544339, 2021). "Here, we will illustrate how NetAct infers TF activity on two cases of microarray KD experiments—one case for shRNA KD of FOXM1 and shRNA KD of MYB in lymphoma cells (GEO: GSE17172), and another case for KD of BCL6 on both OCI-Ly7 and Pfeiffer GCB-DLBCL cell lines (GEO: GSE45838)." (PMID 36575445, 2022). "Importantly, the authors extend their findings on MYC, ZDHHC11/B, MYB upregulation, and mir-150 downregulation also to other lymphoma entities including cHL." (PMID 33544339, 2021). "The MYB gene was discovered from virus MYB (V-MYB), which is the oncogene of avian myeloblastosis virus (AMV) and E26 (another avian virus), and is considered a causative the oncogene of avian myeloma and lymphoma in birds." (PMID 34876130, 2021). "While inputting lymphoma into TMREC and ranking the results, a cascade named TP73 → miR-145 → MYC → miR-15a → MYB → miR-155 → SPI1 → miR-338 with the highest score was obtained." (PMID 25932650, 2015). "This link may suggest that overexpression of HOXA9 or c-MYB is present in a subset of DLBCL, predicting aggressive behavior probably through the expression of a stemness phenotype by lymphoma cells." (PMID 33288848, 2020). "In conclusion, although MYC, MYB and ZDHHC11 all have important roles in the growth of HL and DLBCL, the network, as defined in BL with a critical role of miR-150, is not broadly applicable to other GC B-cell derived lymphoma subtypes." (PMID 35205272, 2022).
pancreatic cancer (14 papers, 2013 to 2025). "MYB, a proto-oncogene encoding a transcription factor, plays a crucial role in pancreatic tumor growth and metastasis." (PMID 40680814, 2025). "We have also reported a critical role of MYB in pancreatic tumor histopathology and associated molecular and biological mechanisms." (PMID 28383487, 2017). "Recently, we established the role of MYB as a novel regulator of pancreatic tumor growth and metastasis as it modulated cancer associated phenotypes such as growth, tumorigenicity, cell cycle, migration and invasion." (PMID 27354262, 2016). "We have recently demonstrated that the transcription factor MYB can modulate several cancer-associated phenotypes in pancreatic cancer." (PMID 27354262, 2016). "Collectively, MYB, its crosstalk with HIF1α, and their coregulated downstream target genes represent attractive targets for therapy and potential biomarkers for risk prediction in pancreatic cancer." (PMID 40680814, 2025). "Our previous work demonstrated a significant role of MYB in supporting the hypoxic survival of pancreatic cancer cells through its induced expression and metabolic reprogramming in cooperation with HIF1α." (PMID 40680814, 2025). "Collectively, our data unfolds a novel reciprocal regulatory crosstalk between MYB and HIF1α, driving optimal adaptation of pancreatic cancer cells under hypoxia." (PMID 40680814, 2025). "We also showed that MYB promotes desmoplasia by enhancing communication between pancreatic cancer and stellate cells." (PMID 40680814, 2025). "Recently, we also revealed a role of MYB in hypoxic survival of pancreatic cancer cells by promoting metabolic reprogramming through interaction with HIF1α, modulating its expression and binding to glycolytic gene promoters." (PMID 40680814, 2025). "To investigate the effect of hypoxia on MYB genomic occupancy, we performed ChIP-seq analysis in pancreatic cancer cells grown under hypoxia and normoxia." (PMID 40680814, 2025). "In summary, our findings reveal a pivotal role for MYB in the transcriptional reprogramming of pancreatic cancer cells under hypoxia, supporting their optimal adaptation and aggressive behavior." (PMID 40680814, 2025). "Recently, we identified MYB as a novel player in the hypoxic survival of pancreatic cancer cells through its interaction with HIF1α." (PMID 40680814, 2025). "Together, these findings highlight the functional significance of reciprocal crosstalk between MYB and HIF1α, providing novel mechanistic insights into pancreatic cancer pathobiology." (PMID 40680814, 2025). "In pancreas cancer, MYB was initially identified as a candidate oncogene due to its amplification in approximately 10% of cancers cases." (PMID 38542205, 2024). "We performed RNA-Seq analysis in MiaPaCa cell line model to generate a general model of MYB-dependent pathways in pancreatic cancer." (PMID 27354262, 2016). "Analyses of the dataset also suggested other novel functions of MYB in pancreatic cancer that warrant in-depth investigation to comprehend their functional relevance and are subject of ongoing research." (PMID 27354262, 2016). "Our findings thus suggest that MYB potentially regulates growth and genomic stability of pancreatic cancer cells via targeting complex gene networks and signaling pathways." (PMID 27354262, 2016). "In order to understand the molecular basis of these MYB-associated changes, we conducted deep-sequencing of transcriptome of MYB-overexpressing and -silenced pancreatic cancer cells, followed by in silico pathway analysis." (PMID 27354262, 2016). "Further in-depth functional studies are warranted to fully understand MYB signaling in pancreatic cancer." (PMID 27354262, 2016). "In summary, we report for the first time various molecular mechanisms regulated by MYB in pancreatic cancer on a systemic level." (PMID 27354262, 2016).
pancreatic cancer (continued). "We recently identified MYB as an important regulator of pancreatic cancer pathogenesis which modulates tumor growth, aggressiveness as well as metastasis." (PMID 27354262, 2016). "RNA-sequencing (RNA-seq) of MYB-expressing pancreatic cancer cells under normoxia (21 % O2) and hypoxia (1.0 % O2) identified 2156 differentially expressed genes (DEGs) (fold change ≥1.5, p value < 0.05), of which 1339 were upregulated and 817 downregulated in hypoxia-exposed cells." (PMID 40680814, 2025). "Previously, we demonstrated a role of MYB in pancreatic tumor growth and metastasis." (PMID 40680814, 2025). "MYB is reported to be amplified in ~10% of pancreatic tumor samples, and interestingly, its amplification was predominantly reported in advanced tumors indicating a strong correlation with the progression and malignant properties of pancreatic adenocarcinoma tumors." (PMID 28383487, 2017). "Importantly, we observed downregulation of the pancreatic adenocarcinoma signaling pathway in MYB-silenced pancreatic cancer cells exhibiting suppression of EGFR and NF-κB." (PMID 27354262, 2016). "Moreover, the MYB-induced changes in gene expression were also verified by ectopic expression of MYB in BxPC3 cell line, further strengthening the role of MYB in pancreatic cancer." (PMID 27354262, 2016). "MYB is generally highly expressed in most pancreatic cancer cells, irrespective of gene amplification, and is responsible for promoting their growth and malignant properties." (PMID 38542205, 2024). "The effects on many critical genes were not only validated in MiaPaCa model, but also verified in a reciprocal model by forced-expression of MYB in non-expressing cell line, further strengthening the role of MYB in pancreatic cancer pathogenesis." (PMID 27354262, 2016).
astrocytoma (13 papers, 2020 to 2025). "CNS_066, initially diagnosed as ganglioglioma, was reclassified as an astrocytoma with MYB or MYBL1 alterations." (PMID 41033792, 2025). "Astrocytomas that harbor recurrent genomic alterations in MYB or MYBL1 are a group of Pediatric-type diffuse low-grade gliomas that were newly recognized in the 2021 WHO Classification of Tumors of the Central Nervous System." (PMID 39422766, 2024). "Most patients with diffuse MYB/MYBL1-altered astrocytoma have a history of epileptic seizures since childhood." (PMID 37920791, 2023). "Most patients with diffuse MYB/MYBL1-altered astrocytoma had epileptic seizures since childhood and symptoms such as movement disorders, behavioral or mnestic changes occur with both encephalopathy and glioneuronal tumors." (PMID 35727368, 2022). "In contrast to the MYB/MYBL1-altered astrocytoma presented here, these tumors are usually not located in the cerebellum and do not contain dysmorphic neurons." (PMID 35727368, 2022).
viral infection (13 papers, 2015 to 2025). "The functions of WRKY, NAC, and MYB transcription factors in imparting resistance to viral infections can be established." (PMID 40336839, 2025). "For instance, overexpression of OsMYB4 in tomato has been shown to confer protection against viral infections, highlighting the significance of MYB in activating defense responses." (PMID 40336839, 2025). "This aligns with the previous findings demonstrating that the ERF, NAC, WRKY, and MYB transcription factors play key regulatory roles in viral infection." (PMID 41157706, 2025). "These published results and current findings emphasize the role of MYB TF family proteins during virus infection." (PMID 36077222, 2022). "However, reports on the involvement of JA‐responsive MYB TFs in regulating viral infections are rare." (PMID 40652551, 2025). "MYB TFs have also been reported to be involved in viral infections." (PMID 40652551, 2025). "Genes with promoters bound by MYB in CAL1, BPDCN PDX, and normal pDCs (n = 353) were enriched in Reactome gene sets related to the pDC lineage, such as “Innate Immune System” and “Viral Infection Pathways”." (PMID 39499902, 2024). "As a result, mice that lacked MYB in their T cells succumbed to chronic but not acute viral infection, highlighting that T cell exhaustion is an essential adaptation to chronic infection." (PMID 35978192, 2022). "Moreover, other defense-related transcription factors, including MYB, bHLH, NAC, and bZIP families, which are involved in plant defense responses to viral infection, were also identified in our study." (PMID 36357910, 2022). "The MYB gene action gets modulated by JA, and it functions by activating the PR genes expression at the site of infection by triggering the SAR and thereby protecting the plant against viral infection." (PMID 33434234, 2021).
breast tumors (12 papers, 2010 to 2024). "MYB overexpression and dysregulation is observed in almost all breast tumours, and is associated with poor prognosis." (PMID 35096852, 2021). "MYB is highly expressed in estrogen receptor positive (ER + ve) breast tumours and tumour cell lines." (PMID 20659323, 2010). "The attractiveness of MYB as a target in this disease is reinforced by the fact that 60 to 70% of all human breast tumors express MYB." (PMID 20659323, 2010). "Further development will require the identification of more appropriate DIAs for clinical use, and of a feasible approach for inhibiting MYB activity in breast tumors." (PMID 20659323, 2010). "We observed that MYB has an essential partner gene—ARNT2—that is low in non-tumor component but is up-regulated in breast tumors." (PMID 24639887, 2014). "We examined the ZEB1/MYB relation more broadly in EMT and in human breast tumors." (PMID 24283570, 2013).
lung carcinoma (12 papers, 2012 to 2023). "The fifth one is hsa-mir-195, which participates in the process of affecting lung cancer by regulating MYB, cyclin D3, Ailanthone." (PMID 32428028, 2020). "These analyses revealed that MYB expression (encoding the c-Myb) is increased in several cancers including breast, colon, and lung cancer as previously reported, and MYB is overexpressed in lung cancer as compared with normal tissues." (PMID 28754957, 2017). "The individual functions of NKX2-1, miR-200c, MYB, and NFIB in lung development and/or lung cancer have been widely documented." (PMID 25763778, 2015). "Besides, NT157 decreased expression of oncogenes BCL2, CCND1, MYB, and MYC and increased genes related to cellular stress and apoptosis, JUN, BBC3, CDKN1A, CDKN1B, FOS, and EGR1 (p < 0.05), favoring a tumor-suppressive cell signaling network in the context of lung cancer." (PMID 36224313, 2022).